G0S2 (G0/G1 switch 2)
Diseases named in the same sentence as G0S2 in open-access papers (continued):
Sharing a sentence is not in itself a finding about the gene and the disease.
embryonal carcinoma (1 paper, 2013). A non-seminomatous malignant germ cell tumor characterized by the presence of large germ cells with abundant cytoplasm resembling epithelial cells, geographic necrosis, high mitotic activity, and pseudoglandular and pseudopapillary structures formation. "Similar inhibitory effects of G0S2 were observed in other retinoid-responsive cell lines including BEAS-2B immortalized human bronchial epithelial and NT2/D1 multipotent human embryonal carcinoma cell lines." (PMID 23546556, 2013).
endometriosis (1 paper, 2021). The growth of functional endometrial tissue in anatomic sites outside the uterine body. "Among the top 20 genes, APOE, DUSP1, MGST1, G0S2, ID4, WEE1, and H2AFZ expression levels were upregulated in the oocytes of patients with endometriosis." (PMID 33467661, 2021).
Hypercholesterolemia (1 paper, 2025). An increased concentration of cholesterol in the blood. "Taken together, these findings provide evidence that G0s2 ablation confers resistance against diet-induced hypertriglyceridemia, as well as reducing the severity of atherogenesis without affecting hypercholesterolemia." (PMID 40100923, 2025). "G0S2 contributes to diet-induced hypertriglyceridemia but not hypercholesterolemia." (PMID 40100923, 2025).
hypertriglyceridemia (1 paper, 2025). A laboratory test result indicating elevated triglyceride concentration in the blood. "Strikingly, transplantation of G0S2-deficient WAT normalized plasma TG levels in mice with hypertriglyceridemia." (PMID 40100923, 2025). "In comparison, transplantation with G0s2–/– fat completely reversed the hypertriglyceridemia, decreasing the plasma TG to levels even below those observed in the chow-fed donors." (PMID 40100923, 2025). "To further establish the link between G0S2 and hypertriglyceridemia, we conducted an oral lipid tolerance test (OLTT) in G0s2–/– mice and their WT littermates." (PMID 40100923, 2025). "Significantly, our findings that the transplantation of G0s2–/– WAT alleviated diet-induced hypertriglyceridemia further underscore the therapeutic potential of targeting G0S2 in lipid metabolism disorders." (PMID 40100923, 2025). "That transplantation of G0s2–/– WAT completely normalized the circulating TG levels in WT recipients with preexisting hypertriglyceridemia strongly indicates an adipose tissue–autonomous effect of G0s2 ablation." (PMID 40100923, 2025). "Transplantation with G0s2–/– WAT alleviates diet-induced hypertriglyceridemia in WT recipient mice." (PMID 40100923, 2025). "Specifically, we tested whether transplantation of WAT from G0s2–/– mice would improve diet-induced hypertriglyceridemia." (PMID 40100923, 2025). "Here, we demonstrate that genetic ablation of G0S2, a specific inhibitory protein of ATGL, completely abolished diet-induced hypertriglyceridemia and significantly attenuated atherogenesis in mice." (PMID 40100923, 2025). "Although G0S2 ablation had no impact on hepatic TG secretion, it enhanced whole-body RER, implying that increased lipid oxidation combined with enhanced TG clearance contributes to mitigating hypertriglyceridemia in these mice." (PMID 40100923, 2025).
hypoglycaemia (1 paper, 2026). "Instead, concurrent hypoglycaemia and hypoinsulinaemia activated a potent catabolic state by suppressing lipid storage and increasing catecholamine-independent lipolysis via downregulation of cell-autonomous lipolytic inhibitors including G0s2." (PMID 41507664, 2026).
hypothyroidism (1 paper, 2020). Abnormally low levels of thyroid hormone. "An opposite effect of hypothyroidism on lipolysis was observed in WT mice, in which lower levels of ATGL, ABDH5, and HSL expression were observed, whereas G0S2 protein levels increased." (PMID 33374300, 2020). "Interestingly, in the heart in SCD1−/− mice, hypothyroidism activated the ATGL pathway, reflected by an increase in the protein content of ATGL and ABDH5 and decrease in the protein content of G0S2." (PMID 33374300, 2020).
leishmaniasis (1 paper, 2024). Infectious disease that is transmitted through the bite of hematophagous female phlebotomine sand flies. "In particular, the results propose that G0S2 and CXCL8 can be potential biomarkers and therapeutic targets for leishmaniasis." (PMID 38190401, 2024).
liver cancer (1 paper, 2025). An epithelial or non-epithelial malignant neoplasm that arises from the liver. "To investigate the expression of G0S2 in liver cancer tissues, we performed mIHC using antibodies against CD14, CD68, and G0S2 on an HCC tissue microarray to enable double staining with the monocyte markers." (PMID 40282408, 2025).
malignant glioma (1 paper, 2018). A grade III or grade IV glioma arising from the central nervous system. "siRNA-mediated knockdown of G0S2 in the U251 malignant glioma cell line significantly suppressed cellular invasion." (PMID 30388142, 2018).
non-alcoholic steatohepatitis (1 paper, 2024). "The up- or downregulation of additional genes that showed sex-specific responses (G0s2, Igfbp1, Mfsd2a, Myc, and Tat), as observed in the male rats, has been reported to increase lipid accumulation and lead to a non-alcoholic steatohepatitis-like phenotype." (PMID 38903859, 2024).
osteosarcoma (1 paper, 2024). A usually aggressive malignant bone-forming mesenchymal neoplasm, predominantly affecting adolescents and young adults. "G0S2 is a G0/G1 switch gene 2 which was observed to be downregulated in osteosarcoma." (PMID 38966281, 2024).
Salmonella Infections (1 paper, 2015). Infections with bacteria of the genus SALMONELLA. "The majority of these genes were assigned different functions in the immune response, however five of them (LOC101750351, K123, BU460569, MOBKL2C and G0S2) have not been associated with the response of chicken to Salmonella infection so far." (PMID 26046914, 2015).
van der Woude syndrome (1 paper, 2022). Van der Woude syndrome (VWS) is a rare congenital genetic dysmorphic syndrome characterized by paramedian lower-lip fistulae, cleft lip with or without cleft palate, or isolated cleft palate. "G0S2 (G0/G1 Switch 2) is a protein-coding gene located in the mitochondria involved in the extrinsic apoptotic signaling pathway, which plays a role in the positive regulation of the extrinsic apoptotic signaling pathway regulating Van der Woude syndrome." (PMID 36360315, 2022).
tumor (33 papers, 2012 to 2026). "In contrast, G0S2, a highly expressed gene in anergic neutrophils, was associated with poor prognosis in several tumor types, including KIRC, stomach adenocarcinoma (STAD), and LUAD." (PMID 38483933, 2024). "Standout upregulated genes include G0-G1 switch gene 2 (G0S2) a tumour suppressor gene associated with human dermal fibroblasts senescence, haematopoietic stem cell quiescence, adipocyte differentiation and cell-cycle withdrawal." (PMID 37314668, 2024). "Numerous studies have reported that G0S2 is associated with tumor cell proliferation." (PMID 40519301, 2025). "Our results demonstrate that G0S2 expression is significantly elevated in both tumor tissues and peripheral blood mononuclear cells of HCC patients." (PMID 40282408, 2025). "By intersecting these genes, we identified three genes (PLA2G2A, DPEP1, and G0S2) that were upregulated in primary and recurrent tumor tissue." (PMID 40519301, 2025). "To further quantify this difference, we calculated the fold change in G0S2 expression (Tumor/Para) for each patient pair." (PMID 40282408, 2025). "Overall, G0S2 expression is significantly higher in tumor tissues compared to para-tumor tissues (p = 0.016)." (PMID 40282408, 2025). "In the in vivo experiments, we found that the combination of anti-PD-1 monoclonal antibody therapy and G0S2 knockout significantly inhibited tumor growth and extended the mouse survival of mice." (PMID 40519301, 2025). "Our data show that approximately 62% of the patient pairs (8 out of 13) exhibit at least a 1.5-fold increase in G0S2 expression in tumor tissues relative to the corresponding para-tumor tissues." (PMID 40282408, 2025). "Taken together, these results demonstrated that the overexpression of G0S2 effectively suppressed the tumor malignant phenotype in PC and promoted the sensitization of PC cells to Gemcitabine." (PMID 39707168, 2024). "Substantial evidence has indicated that G0S2 functions as a tumor suppressor by repressing PI3K/Akt/mTOR activity which is associated with Toll-like/MAPK signaling pathways." (PMID 39707168, 2024). "More importantly, G0S2 overexpression not only inhibited tumor malignant phenotype and drug resistance for Gemcitabine in PC but also effectively reversed the roles of UTX mutant with Toll-like signaling pathway involved." (PMID 39707168, 2024). "Remarkably, hepatocyte areas adjacent to dHGP CRCLM showed upregulation of genes involved in tumor suppression and metastasis inhibition such as G0S2, ITIH2 and DCN." (PMID 36691028, 2023). "Using CML cell lines, patient samples and G0s2 knockout (G0s2−/−) mice, we demonstrate a tumour suppressor role for G0S2 in CML and TKI resistance." (PMID 36536477, 2022). "Ultimately, our data identified a tumour suppressor role for G0S2 in CML survival and TKI resistance that was independent from its canonical function as an inhibitor of ATGL." (PMID 36536477, 2022). "Altogether, these data implicate a tumour suppressor role for G0S2 in CML disease progression and TKI resistance." (PMID 36536477, 2022). "In the present study, we elucidated a role for G0S2 as a tumour suppressor in CML that is downregulated in multiple scenarios of TKI resistance, including TKI non‐responders versus responders, BP‐CML versus CP‐CML, and CP‐CML versus normal myeloid progenitors." (PMID 36536477, 2022). "In a previous report, the G0S2 gene was found in PBMCs and recognized as a potential tumor suppressor gene." (PMID 33061827, 2020). "Knockdown of G0S2 promoted lipid droplet turnover, cell apoptosis, inhibited radioresistance in GSCs, and extended xenograft tumor animal survival." (PMID 30953555, 2019). "In clinical tumor samples, compared to paired normal brain tissues, G0S2 was found highly expressed in three of four clinical GBM tissue samples." (PMID 30953555, 2019). "We further assessed the effect of G0S2 depletion on tumor growth in the brain of mice in response to IR treatment." (PMID 30953555, 2019).
tumor (continued). "Compared with paired normal brain tissues, we further found that the level of G0S2 expression was elevated in clinical tumor specimens." (PMID 30953555, 2019). "Expression of G0S2 is downregulated in a wide variety of cancer cell types and has the properties of tumor suppressor." (PMID 30175151, 2018). "G0S2 exerts tumor suppressive functions because G0S2 expression is required to commit cells to enter the G1 phase of the cell cycle." (PMID 29073263, 2017). "Findings from several groups demonstrated that expression of G0S2 is silenced across a wide-range of tumor types." (PMID 26318046, 2015). "Inhibition of ATGL by G0S2, RNAi, or a small molecule inhibitor was able to attenuate the growth and motility of tumor cells." (PMID 26318046, 2015). "The study of endogenous G0S2 in cancer cells is complicated by the fact that the gene is highly methylated and silenced in most tumor-derived cell lines." (PMID 26318046, 2015). "Like in many other tumor cells, the promoter of G0S2 was shown to be methylated in K562 cells is reversed using the methylation inhibitor 5-Azacytadine (5-Aza)." (PMID 26318046, 2015). "Second, ectopic expression of G0S2 in a variety of human tumor cells promotes cell death and can also inhibit proliferation of hematopoietic stem cells and CML." (PMID 26318046, 2015). "Our data uncover a novel tumor suppressor mechanism by which G0S2 directly inhibits activity of a key intracellular lipase." (PMID 26318046, 2015). "In the current study we show that the tumor suppressor properties of G0S2 are derived at least in part from its capacity to inhibit ATGL." (PMID 26318046, 2015). "In the current study we show for the first time that the inhibition of ATGL by G0S2 can significantly reduce the growth and motility of a variety of tumour cell lines." (PMID 26318046, 2015). "Existing studies have shown that G0S2 can regulate lipid metabolism and apoptosis, which may influence tumor cells and immune cells through different mechanisms [7,8,9,11,12,13,]." (PMID 40282408, 2025). "High expression of G0S2 in these cells may help maintain their immunosuppressive functions, thereby further supporting tumor growth and dissemination." (PMID 40282408, 2025). "Notably, the combination of G0S2 knockout and anti-PD-1 antibody treatment significantly suppressed tumor volume and prolonged mouse survival." (PMID 40519301, 2025). "Additionally, we found that G0S2 influenced the type I interferon signaling response in tumor cells and exhibited strong antitumor effects when combined with anti-PD-1 therapy." (PMID 40519301, 2025). "An immunohistochemical analysis demonstrated that G0S2 expression was significantly higher in the tumor tissues compared to the adjacent non-tumorous tissues, further confirming its important role within the tumor microenvironment." (PMID 40282408, 2025). "This elevated expression in the tumor tissues suggests that higher G0S2 levels may correlate with reduced sensitivity to PD-1 therapy, considering that PD-1 antibodies achieve response rates of around 30–40% in HCC." (PMID 40282408, 2025). "Our study elucidates the therapeutic value of targeting G0S2 in tumor contexts." (PMID 40519301, 2025). "To further validate the role of G0S2, we knocked out G0S2 in tumor cells." (PMID 40519301, 2025). "The high expression of G0S2 in monocytes may thus be a key factor in tumor immune escape and resistance to PD-1 inhibitors." (PMID 40282408, 2025). "Numerous studies have identified the specific interaction between G0S2 and Bcl-2 at the mitochondria, disrupting the formation of the Bcl-2/Bax anti-apoptotic heterodimer complex, thereby regulating its anti-apoptotic activity in human tumor cells." (PMID 39707168, 2024). "We further explored whether UTX-regulated G0S2 and Toll-like signaling pathways affect Gemcitabine’s anti-tumor effect on PC cells." (PMID 39707168, 2024).
tumor (continued). "To sum up, we determined that UTX might act as a tumor suppressor in PC by promoting the expression of G0S2, while the mutant UTX partially loses this function." (PMID 39707168, 2024). "According to a previous study, G0S2 interacts with Bcl-2 and promotes apoptosis in tumor cells." (PMID 35769488, 2022). "Previous studies have shown G0S2 to be both oncogenic and tumor suppressive." (PMID 30953555, 2019). "That G0S2 functions as an oncogene or tumor suppressor may be related with G0S2 lipolytic inhibitor activity." (PMID 30953555, 2019). "As a protein participating in cell cycle regulation, G0S2 acts as a tumor suppressor." (PMID 30367950, 2019). "The upregulation of G0S2 has shown a significant reduction in tumor cell growth and motility." (PMID 30175151, 2018). "Moreover, G0S2 expression was higher in recurrent tumor specimens than at the initial diagnosis in the same patient." (PMID 30388142, 2018). "Although several binding partners have been shown for G0S2 including Bcl2, ATGL and Nucleolin, our studies suggest that inhibition of ATGL can attenuate cell growth in a wide range of tumour cells and is an important mechanism of G0S2-mediated growth inhibition." (PMID 26318046, 2015). "ATRA is the frontline therapy for APL and the induction of G0S2 expression in this system suggests that the tumor suppressor properties of the protein may play a role in the response to the drug." (PMID 26318046, 2015). "Three properties of G0S2 suggest that the protein functions as a tumor suppressor." (PMID 26318046, 2015). "Since G0S2 overexpression resulted in elevated TG levels in A549 and HOP62 cells, we hypothesized that ATGL inhibition may explain some of the tumor suppressor properties displayed by G0S2 in NSCL." (PMID 26318046, 2015). "Existing studies suggest that G0S2 may have dual roles in multiple cancer types, potentially acting as a tumor suppressor by regulating the cell cycle and apoptosis, while also supporting tumor cell growth and survival through metabolic pathway modulation." (PMID 40282408, 2025). "This suggests that G0S2 may play a pivotal role in tumor immune escape by regulating TAMs." (PMID 40282408, 2025). "Thus, the role of G0S2 as a tumour suppressor in CML and in normal myeloid differentiation could depend on its LPAAT enzymatic activity and the ability to synthesise PA, which will be the topic of future investigation." (PMID 36536477, 2022). "In addition, G0S2 is recognized as a potential tumor suppressor gene, which may explain why the side effects of tacrolimus lead to tumorigenesis." (PMID 33061827, 2020). "We observed that G0S2 knockout alone was sufficient to suppress tumor growth in mice, whereas administration of the IFNAR1 inhibitor in the control group promoted tumor growth." (PMID 40519301, 2025). "The results indicated that in GBM tumor tissue, OSMR and FMOD were primarily distributed in astrocytes, IGFBP6 in NPC, G0S2 in macrophages, and IGHG2 in T cells." (PMID 39815665, 2025). "To investigate the role of the five genes (OSMR, G0S2, IGFBP6, IGHG2, and FMOD) in specific cells within the tumor tissue of GBM patients, we illustrated the distribution of these genes across different cell types." (PMID 39815665, 2025). "In summary, the mRNA expression of OSMR, G0S2, IGHG2, and FMOD was significantly upregulated in tumor tissue of GBM patients compared to normal control tissue." (PMID 39815665, 2025). "Besides, G0S2 could function as a tumor suppressor by opposing c-Myc." (PMID 36366842, 2023). "In both tumor and normal lung tissue of all core atlas samples, the neutrophil cluster (FCGR3B, CSF3R, CXCR2, and G0S2) comprised 8,468 cells with overt low mRNA counts." (PMID 36368318, 2022). "Interestingly, both Wnt and G0S2 are physiologically implicated in the inhibition of adipogenesis, suggesting that common mechanisms between ACC tumor progression and ASC reprogramming might occur in the tumor microenvironment." (PMID 32478073, 2020).